CRP (C-reactive protein)
Diseases named in the same sentence as CRP in open-access papers (continued):
Sharing a sentence is not in itself a finding about the gene and the disease.
anemia (continued). "Having higher serum C-reactive protein and lactic dehydrogenase levels and the presence of a more advanced stage for international staging system (ISS), anemia and extramedullary tumors are the main poor prognostic factors of MM." (PMID 18831763, 2008). "Laboratory tests revealed elevated serum C-reactive protein (CRP) of 152 mg/L, macrocytic anemia with a hemoglobin of 6.2 g/dL and a mean corpuscular volume of 116.5 fL, neutrophilia of 14,400 μL, 23% of which were rods (3,319 μL), and thrombocytopenia of 53,000 μL." (PMID 41187472, 2025). "Among WRA, anemia was 31%; prevalences of MNDs were: iron, 45%; zinc, 79%; vitamin A, 1%; B-12, 12%; and folate, 12%; with 15% elevated α1‐acid glycoprotein (AGP) or C-reactive protein (CRP)." (PMID 40526587, 2025). "Laboratory tests revealed new-onset neutropenia, mild anemia (grade 1) initially attributed to chronic disease, and cholestatic liver enzyme abnormalities (GGT > 400 U/L, ALP > 200 U/L), along with elevated C-reactive protein (CRP 4.14 mg/dL)." (PMID 41441532, 2025). "Other symptoms include fatigue, cough, fever, arthralgia, myalgia, weight loss, and erythematous rash, and laboratory findings are non-specific (anemia, increased erythrocyte sedimentation rate, increased level of C-reactive protein, and gamma globulin)." (PMID 40506961, 2025). "Studies have shown that the severity of anemia in TB patients can correlate with markers of disease activity, such as elevated inflammatory cytokines (e.g., interleukin 6 (IL-6) and tumor necrosis factor alpha (TNF-α)) and C-reactive protein (CRP) levels." (PMID 40698207, 2025). "Clustering was performed using perioperative characteristics (age, operative duration, anemia, CRP, ASA score, and surgical delay) independent of infection status to identify natural patient subgroups." (PMID 41302186, 2025). "Laboratory tests revealed no significant findings apart from mild anemia and an elevated C-reactive protein (CRP) of 38 mg/L." (PMID 41144145, 2025). "Findings revealed mild anemia and hypoproteinemia, along with elevated erythrocyte sedimentation rate and C-reactive protein, with no additional abnormalities." (PMID 41531633, 2025). "Laboratory findings in the case descriptions were anemia, thrombocytopenia, hyperbilirubinemia, elevated liver enzymes, elevated inflammation markers (CRP), hematuria, negative serological investigation (bacterial and viral tests)." (PMID 40919226, 2025). "After 4 months, we had her follow-up that revealed anemia was corrected, and ESR CRP were normal." (PMID 40176882, 2025). "Additionally, compared with normal group, participants with anemia were found to be older and showed elevated levels of WBC, Neutrophil ratio, PCT, CRP, serum G test positive rate, GM test positive rate, BUN, creatinine and D-dimer." (PMID 41179861, 2025). "CRP production (primarily regulated by IL-6 and indirectly by TNF-α) and TNF-α’s direct suppression of erythrocyte progenitor cell proliferation both contribute to anemia." (PMID 41179861, 2025). "Initial laboratory investigations revealed mild anemia, elevated C-reactive protein (CRP), prolonged prothrombin time (PT) and international normalized ratio (INR), with normal white blood cell count (WBC) and procalcitonin levels." (PMID 40395273, 2025). "Following reintroduction, abdominal pain resolved, and stool frequency decreased to 6 per day (without blood), although CRP remained elevated (18.2 mg/L) and anemia persisted (Hb 7.8 g/dL, MCV normalized)." (PMID 41011540, 2025). "The combination of low transferrin saturation, high ferritin, normal transferrin receptor levels, and elevated CRP in these patients suggests anemia of chronic disease rather than classic IDA." (PMID 39863874, 2025). "A significantly higher percentage of patients with anemia had elevated CRP levels compared to the non-anemic patients (71% vs. 39%, p < 0.001)." (PMID 40636681, 2025).
anemia (continued). "Laboratory findings include various degrees of anaemia of chronic disease, elevated acute-phase reactants (such as erythrocyte sedimentation rate and serum C-reactive protein) and negative RF and ACPA." (PMID 39044899, 2024). "We created a highly accurate (c-index 0.87) long-term prognostic scoring system called the CACHEXIA score (Cancer including metastasis tumor, blood tumor, and bleeding from tumor, Albumin, Cirrhosis, High PS, EXtremely thin (i.e., low BMI), Increased CRP and BUN, Anemia (i.e., blood transfusion))." (PMID 38438534, 2024). "This study discusses a middle-aged female FM patient who developed elevated CRP and anemia and was eventually diagnosed with non-secretory multiple myeloma during a two-year follow-up." (PMID 39070404, 2024). "In addition to low hemoglobin levels, these TB-related anemia patients also showed elevated WBC, CRP, LDH and ESR." (PMID 38886797, 2024). "Blood tests showed a microcytic anaemia [Hb 11.4 g/dl, MCV 67.7 fl], normal blood leucocyte count with relative neutropenia and lymphocytosis, hyponatremia [132.6 mEq/l], a slight increase in the CRP levels [0.74 mg/dl] with hyperferritinemia [673.6 ng/ml]." (PMID 38888722, 2024). "Another advantage is that CRP is not affected by conditions such as anemia, polycythemia, protein levels, red blood cell shape, sex, or an important factor like the patient’s age and other types of inflammatory diseases." (PMID 39595661, 2024). "Laboratory investigations revealed anemia, leukopenia, thrombocytopenia, increased creatinine, aminotransferases, creatine phosphokinase (CPK), lactate dehydrogenase (LDH), and C-reactive protein (CRP)." (PMID 38892108, 2024). "Typical laboratory findings in MIS-C include lymphopenia, neutrophilia, thrombocytopenia, moderate anemia, abnormal pathological values of inflammatory markers such as ESR, CRP, fibrinogen, ferritin, PCT, and IL-6, and elevated LDH levels, hypoalbuminemia, and hyponatremia." (PMID 39597816, 2024). "Secondary objectives were to study the impacts of BC with LDS on anthropometry and especially on weight gain, anemia and need for blood transfusion, feeding tolerance, and stage II and III of NECas well as its anti-inflammatory effect indirectly evaluated through CRP levels analysis." (PMID 39427215, 2024). "The patient showed slight anemia (Hb: 11.8 g/dL) and elevation of inflammatory reaction (CRP: 5.98 mg/dL) without positive tumor markers." (PMID 39523235, 2024). "Nineteen indicators relevant to the anemia prediction model for patients with osteosarcoma after chemotherapy were identified, including Gender, Surgery, LYM, MO, LYM%, BLT, TP, ALB, CA, CREA, APTT, FIB, D‐dimer, CRP, ESR, PCT, IgA, CEA, and CA.153." (PMID 39621534, 2024). "On further analysis, a lack of resolution of preoperative anemia, hypercalcemia, elevated CRP, elevated ESR, or elevated LFTs were all independently associated with worse OS and CSS." (PMID 39518116, 2024). "Certain correction studies indicate that roxadustat ameliorates anemia in patients undergoing HD regardless of baseline C-reactive protein levels, and its dosage requirements are less affected by inflammation compared to ESAs." (PMID 39771061, 2024). "A medical checkup in a 35-year-old woman revealed a high C-reactive protein (CRP) level and anemia; however, the woman did not undergo any further examination." (PMID 39776937, 2024). "Laboratory investigations indicated anemia, neutrophil-predominant leukocytosis, elevated liver transaminases, hyperferritinemia, an elevated erythrocyte sedimentation rate (ESR), and a high C-reactive protein (CRP)." (PMID 38966488, 2024). "A laboratory workup could reveal findings suggestive of anemia of chronic disease with normal or mild elevation in inflammatory markers, such as erythrocyte sedimentation rate (ESR) and C-reactive protein (CRP)." (PMID 37692753, 2023).
anemia (continued). "Blood tests revealed severe inflammation (white blood cell [WBC] count, 12,340/μL; C-reactive protein [CRP], 21.0 mg/dL), anemia (hemoglobin, of 9.9 g/dL), poor nutrition (serum albumin, 1.8 g/dL), and chronic kidney disease (blood urea nitrogen, 41.8 mg/dL; serum creatinine, 1.97 mg/dL)." (PMID 37199823, 2023). "However, after 3 months CNS inflammation persisted (ongoing seizures with evidence of persistent neuroinflammation on repeat brain MRI), anemia returned, and acute phase reactants deteriorated (ESR 60 mm/h; SAA 82.9 mg/L; CRP 9 mg/L)." (PMID 37744344, 2023). "No statistical differences were found regarding anemia, elevated CRP or elevated fecal calprotectin." (PMID 37608313, 2023). "The WBC, CRP, and ESR returned to normal, as did anemia, very soon post-treatment." (PMID 37809096, 2023). "Inflammatory features of DADA2 can include recurrent fevers, mild to moderate anemia, and elevated inflammatory markers, such as erythrocyte sedimentation rate (ESR) and C-reactive protein (CRP) and musculoskeletal involvement (arthralgia/arthritis and/or myalgia/myositis)." (PMID 36807221, 2023). "A laboratory examination revealed high inflammation marker levels, mild anemia, and hypoalbuminemia, with white blood cell (WBC) count of 11,060/μL, hemoglobin of 12.9 g/dL, platelet count of 33.3 × 104/μL, C-reactive protein (CRP) of 4.43 mg/dL, and albumin of 3.7 g/dL." (PMID 37443475, 2023). "Laboratory testing includes elevated C-reactive protein (CRP), anaemia, hypoalbuminaemia, and faecal biomarkers such as faecal calprotectin (fCP), the latter being frequently used to distinguish irritable bowel syndrome (IBS) from IBD as well as monitoring treatment response and disease activity." (PMID 35407486, 2022). "Quiescent IBD was defined as clinical (Harvey-Bradshaw Index < 5 or Simple Clinical Colitis Activity Index < 2.5) and biochemical remission (C-reactive protein < 5 mg/L and absence of anemia) at time of fatigue assessment." (PMID 36028644, 2022). "Lab tests did not reveal anemia, thrombocytopenia, hypoalbuminemia, elevated CRP, or renal dysfunction." (PMID 36247763, 2022). "SSc patients with anemia had higher ESR (56.6% in anemia vs. 25.5% in non-anemia, p < 0.001) and CRP levels (28.1% in anemia vs. 17.2% in non-anemia, p = 0.010)." (PMID 36078943, 2022). "In our study, a negative correlation was found between CRP and HCT, which supports the studies indicating that chronic inflammation causes anemia." (PMID 35208487, 2022). "Laboratory tests showed anemia (Hb 7.2 g/dL), mildly elevated eosinophil percentage (up to 10.4%, absolute count 1,050/μL), thrombocytosis (platelet 825,000/μL), hypoalbuminemia (albumin 1.94 g/dL), normal INR, and normal CRP levels." (PMID 35450101, 2022). "In the present study, independent of anemia, CRP, and procalcitonin, indicators of inflammation were found to be statistically higher in the patient group with NOAF." (PMID 35892443, 2022). "Erythrocyte sedimentation rate (ESR)and C-reactive protein (CRP) may be elevated, and anemia of chronic disease maybe observed." (PMID 39077599, 2022). "Second, hyperventilation was not contingent on evident and expected potential triggers such as anaemia (expressed by haemoglobin, haematocrit), infection (expressed by WBC, CRP, IL-6, IL-22), hypoxemia (expressed by pO2 and sO2) or pulmonary congestion on physical examination." (PMID 36207364, 2022). "Anemia remained a strong negative predictor of survival also when patients were stratified by baseline CRP, but a stronger negative effect of anemia on survival was found in the group of patients with CRP <0.7 mg/dL." (PMID 35895618, 2022). "However, in this study, we did not investigate the causes of anaemia or perform additional investigations to differentiate the causes of anaemia such as serum iron, ferritin, vitamin B12/Folate levels, and inflammatory markers such as C-reactive protein or erythrocyte sedimentation rate." (PMID 36205691, 2022).
anemia (continued). "Non-responsive dogs were more likely to present with anemia, hypoproteinemia, hypoalbuminemia, increased C-reactive protein concentrations, and ascites." (PMID 35739843, 2022). "Simultaneously, we discovered that non-anaemia women had significantly lower CRP concentrations (me = 2.27 mg/L) than non-anaemia men (me = 7.56 mg/L, p = 0.044504) and anaemia men (me = 15.06 mg/L, p = 0.002675)." (PMID 36612220, 2022). "The patient was referred to Hamanomachi Hospital due to mild elevation of C-reactive protein and mild anemia on medical checkup without any symptoms." (PMID 35223247, 2022). "Similarly, in our case we found severely elevated CRP and ESR, lymphopenia, anemia, increased D-dimer and ferritin, hypertriglyceridemia, but also thrombocytopenia." (PMID 36474612, 2022). "When preoperative parameters were compared between patients with anemia and non-anemic patients, patients with anemia were on average significantly older, had higher C-reactive protein (CRP) concentrations, lower transferrin and lower transferrin saturation." (PMID 35895618, 2022). "Initial laboratory evaluation showed anemia, high C-reactive protein (CRP) without procalcitonin (PCT) elevation, and mild leukocytosis." (PMID 36271343, 2022). "Non-responsive dogs were more likely to present with anemia hypoproteinemia/albuminemia, increased CRP, and ascites (p < 0.05)." (PMID 35739843, 2022). "Statistical analyses revealed that males with anaemia on admission to the hospital were not only older than non-anaemia patients in our study group, but they also had the highest CRP concentrations, above reference values (>5 mg/L)." (PMID 36612220, 2022). "After having excluded women with elevated CRP concentration >5 mg/l (9–26 % by ethnic groups), only minor changes in the mean and median values and in the prevalence of ID and anaemia across ethnic groups were observed (data not shown)." (PMID 35754987, 2022). "Second, there are several other risk factors of SSI that were not evaluated in this study, including anemia, preoperative level of C-reactive protein, patient frailty, and procalcitonin." (PMID 33397364, 2021). "Laboratory evaluation showed no anemia, no inflammatory parameters and negative urinary pregnancy test (hemoglobin 12.2 g/dL; C-reactive protein [CRP] 3.7 mg/L)." (PMID 33436080, 2021). "Patients with any hip involvement had later JIA onset age, longer JIA course, higher laboratory inflammatory activity (CRP and ESR levels, anemia, leuko-, and thrombocytosis), a higher number of clinically active joints, high distribution of HLA B27, and more often belonged to the ERA JIA category." (PMID 34805045, 2021). "The inflammatory markers (CRP, WBC count) but not anemia (Hb, Htk) were closely associated with severe renal dysfunction." (PMID 34485326, 2021). "Moreover, the highest tertile of the anemia–inflammation-related dietary pattern was more likely to decrease Hb, Hct, and RBC levels but increase WBC and CRP levels compared to the lowest tertile of the dietary pattern." (PMID 33810272, 2021). "Anaemia was present in 67% of patients, 68% had lymphopenia, 62% had ferritin value > 500 mcg/L, 85% had elevated lactate dehydrogenase (LDH), 83% D-dimer > 500 ng/mL and 80% C-Reactive Protein > 8 mg/L." (PMID 34267802, 2021). "The prevalence of VAD and CRP > 10 mg/L was significantly higher in AI, as compared to participants without anemia (p < 0.05)." (PMID 34836070, 2021). "Unlike the patients with absolute iron deficiency anemia, the subjects in “low TSAT low iron” group have higher malnutrition-inflammation, ferritin and CRP levels and lower TIBC values." (PMID 33863963, 2021). "Feature analysis indicated that strong prognostic markers expectedly included CRP levels, but also markers of organ damage, including kidney injury (creatinine and blood urea nitrogen), liver injury (ALAT), cell damage (LDH), anaemia (haemoglobin levels) as well as ferritin levels." (PMID 33547335, 2021).
anemia (continued). "The artificial MRSA infection through the acute injury promotes the changing of blood profile such as total erythrocytes, leukocytes, neutrophils, lymphocytes, total plasma protein, CRP, the subset of circulatory CD4+, CD8+, and COX-2 and leads to anemia macrocytic normochromic." (PMID 34566324, 2021). "However, he had persisting mild anemia (hemoglobin 12.5 g/dL), eosinophilia (eosinophils 890 cells/μL), and elevated inflammatory markers including ESR (36 mm/hour) and CRP (17.3 mg/dL)." (PMID 34955100, 2021). "Analysis showed normocytic normochromic anemia (Hb 6 g/dL), metabolic acidosis, elevation of ESR (88 mm/first hour) and CRP (3.87 mg/dL), increased serum urea (171 mg/dL) and creatinine (7.7 mg/dL), nonnephrotic proteinuria (484 mg/24 h), haematuria, and leukocyturia without cellular casts." (PMID 34123446, 2021). "Her blood tests and chest X-ray scan showed the presence of anemia (7.5 g/dL), of an inflammatory syndrome (erythrocyte sedimentation ratio [ESR] – 100 mm/h, C-reactive protein [CRP] – 170 mg/dL), and of radiologic alterations suggestive for interstitial pneumonia and bilateral pleural effusion." (PMID 34941099, 2021). "In addition, subjects in the highest tertile of the dietary pattern had worse anemia biomarkers and increased WBC and CRP levels (all p < 0.001), in all the models, compared to those in the lowest tertile of the dietary pattern." (PMID 33810272, 2021). "Moreover, median CRP as well as median HBI (for CD) and median SCAAI (for UC) were higher and median IBDQ was lower in patients with anemia." (PMID 34187376, 2021). "Patients with anemia had a significantly lower FEV1 (43.19 ± 17.57 vs 51.49 ± 17.09%, p=0.03) and DLCOc (48.35 ± 17.74 vs 61.12 ± 21.78%, p=0.01), as well as higher CRP levels (0.77 ± 0.55 vs 0.54 ± 0.75 mg/dl, p<0.01) compared to subjects without anemia irrespective of the presence of ID." (PMID 32922186, 2020). "In logistic regression analysis, higher BDI scores were related to anemia independent of sex, age, inflammation (CRP and neopterin), and UICC stage (HR 1.162 (95% CI 1.059–1.275), p = 0.002)." (PMID 33053619, 2020). "At admission, her blood tests revealed microcytic anemia (Hb 6.5 g/dl, MCV 60.9 fl, RDW 19.4%), raised C-reactive protein (CRP 125 mg/L, range <5 mg/L) and procalcitonin (9.2 ng/ml, range <0.1 ng/ml), leukocytosis (WBC 21,600 cells/mmc) with neutrophilia (ANC 17,170 cells/mmc)." (PMID 32676075, 2020). "Most patients had increased inflammatory markers (CRP and/or ESR) and suffered from anemia." (PMID 32323167, 2020). "The following laboratory abnormalities were noted before referral: leukopenia and anemia, increased erythrocyte sedimentation rate (ESR) and elevated C-reactive protein (CRP) level, increased d-dimer concentration, positive anti-dsDNA antibodies, erythrocyturia and proteinuria (1.0 g/l)." (PMID 31823041, 2020). "There were 20 patients (69%) showed anemia, 19 (65.5%) with increased erythrocyte sedimentation rate (ESR), 18 (62.1%) with increased C-reactive protein (CRP), 11 (37.9%) with reduced albumin, 10 (34.5%) with abnormal leukocytes and 2 (6.9%) with of thrombocytopenia." (PMID 33208100, 2020). "Interaction analyses highlighted the useful situation for assessing the CONUT score for infection in patients without anemia and renal dysfunction, those with high CRP levels, relatively younger patients with age <80 years." (PMID 32094392, 2020). "In our study, WBC, CRP, ESR and anemia were significantly higher in KDSS patients." (PMID 30611297, 2019). "Blood investigations may show anaemia, leukocytosis (shift to left) raised erythrocyte sedimentation rate (ESR) and CRP." (PMID 31249741, 2019). "Overall, 60.2% were women, 33% had CRP values higher than 5mg/L, 7.7% had AGP values higher than 1g/dL, 41.8% had a functional disability as defined by IADL, 35.9% had anemia, 9.4% had VDD, 2.4% had VAD after correcting for inflammation, 5.1% were ID, 9.2% were B12D." (PMID 31052280, 2019).